TRAF2 (TNF receptor associated factor 2)
Diseases named in the same sentence as TRAF2 in open-access papers (continued):
Sharing a sentence is not in itself a finding about the gene and the disease.
osteoporosis (1 paper, 2025). A condition of reduced bone mass, with decreased cortical thickness and a decrease in the number and size of the trabeculae of cancellous bone (but normal chemical composition), resulting in increased fracture incidence. "The interaction between TRAFs, particularly TRAF2, and Smad signaling has garnered attention in research on osteoporosis due to its impact on bone health, especially in osteoblast differentiation and bone formation." (PMID 40496246, 2025). "In osteoporosis, TRAF2 is thought to inhibit BMP signaling as TNF-α exposure results in decreased phospho-Smad1, BMPR-IA, and Runx2 levels, while BMPR-IB and BMPR-II levels increase." (PMID 40496246, 2025).
pancreatic adenocarcinoma (1 paper, 2013). "Next we determined if a similar reverse correlation between NIK expression and activity and TRAF2 downregulation occurs in human samples of pancreatic adenocarcinoma." (PMID 23301098, 2013).
paraganglioma (1 paper, 2024). A benign or malignant neoplasm arising from paraganglia located along the sympathetic or parasympathetic nerves. "Conversely, TRAF2 was identified as a high-risk gene in ACC, COAD, KIRC, LGG, LIHC, MESO, and pheochromocytoma and paraganglioma (PCPG) (HR > 1, P < 0.05)." (PMID 38825674, 2024).
perineurioma (1 paper, 2018). A usually benign perineurioma not associated with a nerve, arising from the soft tissues. "In particular, loss-of-function genetic alterations of TRAF2 and TRAF3 are frequently detected in B cell malignancies, and the rates of missense mutations of TRAF7 are overwhelmingly high in adenomatoid tumors, secretory meningiomas and perineuriomas." (PMID 30294322, 2018).
Pituitary Adenomas (1 paper, 2024). "This study investigated the relationship between specific gene polymorphisms (TRAF2, TAB2, IKBKB) and protein levels and pituitary adenomas (PAs)." (PMID 39061149, 2024). "This study investigated the association of TRAF2 rs867186, TAB2 rs237025, and IKBKB rs13278372 polymorphisms with pituitary adenoma (PA) in a case–control study involving 459 subjects (139 PA patients and 320 controls)." (PMID 39061149, 2024).
prion disease (1 paper, 2024). A transmissible disease that is caused by a protein that is able to induce abnormal folding of normal cellular proteins, leading to characteristic spongiform brain changes, which are associated with neuronal loss without an inflammatory response. "Similarly restoring RIPK1, TRADD and TRAF2 expression would be direct clinical implications on prion diseases." (PMID 38802941, 2024). "Taken together, the results represent diminished TRAF2 expression in mouse prion disease." (PMID 38802941, 2024). "Conversely, the deficiency in TRADD and TRAF2 might weaken neuronal and oligodendrocyte cell survival pathways while amplifying TNFα-TNFR1-RIPK1-FADD-caspase-8 mediated cell death pathways, presenting a complex landscape of cellular fate determination in prion disease pathology." (PMID 38802941, 2024). "Interestingly, not a single study so far has focused into the crucial role of TRADD, TRAF2, FADD, and RIPK1 in prion diseases." (PMID 38802941, 2024).
renal tumor (1 paper, 2023). "Our small animal bioluminescent imaging monitoring results showed that TRAF2 depletion led to decreased renal tumor growth." (PMID 37415241, 2023).
sarcoma (1 paper, 2018). A usually aggressive malignant neoplasm of the soft tissue or bone. "It is also noteworthy that genetic alterations of TRAF2 are detected in 2.6% (7/265) of human sarcomas (TCGA) and TRAF2−/− mice display decreased viability of skeletal muscle tissue because of defective TNFα-induced NF-κB activation in myotubes." (PMID 30294322, 2018).
tubular adenocarcinoma (1 paper, 2019). An infiltrating adenocarcinoma in which the malignant cells form tubular structures. "TRAF2 was expressed at significantly higher levels in tubular adenocarcinoma." (PMID 31130821, 2019).
tumor (120 papers, 2013 to 2026). "We further analyzed the association between TRAF2 expression levels and the extent of tumor-infiltrating immune cell infiltration in TME using the TIMER2.0 database." (PMID 40144665, 2025). "In those parallel screens, the loss of TRAF2 was able to sensitize all but one tumor cell line to T cell attack." (PMID 37398651, 2023). "Receptor-associated factor 2 (TRAF2) was identified as a gatekeeper of TNF cytotoxicity threshold in tumours, by suppressing RIPK1-dependent cell death." (PMID 37503572, 2023). "It is worth mentioning that there is evidence from tumor-associated macrophages that TRAF2 also promotes proteasomal degradation of cRel." (PMID 35681583, 2022). "Baicalin promotes the transformation of tumor-associated macrophages (TAMs) from M2- to M1-like phenotypes through the autophagy degradation of TRAF2 to exert anti-tumor effects." (PMID 35844489, 2022). "Follow-up in vitro and in vivo experiments indeed indicated that TRAF2 deficiency sensitizes tumor cells for killing by TNF expressed by CD8+ T cells." (PMID 36011046, 2022). "Tumor necrosis receptor-associated factor 2 (TRAF2) was overexpressed in the Hot-tumor cluster tumors, compared to the Cold-tumor cluster at both mRNA and protein levels (Fold change > 2; Wilcoxon rank-sum test, p ≤ 0.061)." (PMID 35659036, 2022). "As a result, loss of mLST8 ubiquitination by either mutating the K305/K313 or depleting the E3 ligase TRAF2 enhances mTORC2 activation and tumor growth, while knockout of the deubiquitinase OTUD7B exhibits opposite phenotypes." (PMID 33670113, 2021). "When treated with agonist anti-4-1BB immunotherapy, TRAF2-deficient mice displayed delayed and less efficient tumor rejection, consequently carrying larger subcutaneous CT26 colorectal tumors." (PMID 34639141, 2021). "Clinical information such as age, sex, smoking, alcohol, body mass index (BMI), fasting state, tumor stage and node status was available for the majority of diagnostic samples, and the impact of these clinical factors on TRAF2 levels were studied." (PMID 34888239, 2021). "Following CPI treatment, the potentially deleterious impact of TRAF2 loss on tumor cell fitness is revealed, where it has potential to enhance anti-tumor T cell activity." (PMID 33508232, 2021). "In vivo, diterpenoid Tan promoted lung PC9 cell apoptosis in a dose-dependent manner, up-regulated Bip, IRE1, and TRAF2 protein expressions in tumor tissues, reduced tumor weight and alleviated weight loss." (PMID 36046197, 2020). "In gastric cancer, it was found that high TRAF2 expression was associated with tumor invasion and metastasis and was an important prognostic indicator." (PMID 32566659, 2020). "The expression level of TRAF2 was positively associated with degree of differentiation, depth of tumor invasion, lymph nodes invasion, and TNM stage." (PMID 31130821, 2019). "It has been shown that TRAF2 expression is markedly increased in GC tissues, which is associated with tumor invasion and metastasis." (PMID 31130821, 2019). "In vitro examination of the metastatic behavior of parental and osteotropic cells confirmed that TRAF2 overexpression is linked to increased tumour cell motility and invasion, whereas knockdown of TRAF2 was inhibitory." (PMID 29311633, 2018). "TRAF2 regulates inflammatory cytokine production in tumor-associated macrophages, which facilitates tumor growth." (PMID 30294322, 2018). "We found that, mechanistically, EI24 attenuated NF-κB activity by binding to the Complex I component TRAF2 and causing its lysosome-dependent degradation, thereby suppressing the transcription of pro-inflammatory genes that contribute to tumor progression." (PMID 24280371, 2013). "Additional analyses suggested that TRAF2 may contribute to tumor progression through epigenetic regulation and associated signaling pathways." (PMID 42293334, 2026).
tumor (continued). "TRAF2 is associated with the levels of various immune checkpoint genes and multiple tumor-infiltrating immune cells, suggesting its potential involvement in tumor microenvironment." (PMID 40144665, 2025). "To evaluate the clinical significance of TRAF2/autophagy signaling axis in promoting M2-polarized tumor-associated macrophage infiltration, angiogenesis, and cancer progression, we detected the expression of TRAF2, CD31, LC3, and CD206 in cancerous tissues of patients with ccRCC." (PMID 37415241, 2023). "Moreover, TRAF2 protein levels in HCC were prominently associated with the clinicopathological parameters such as the tumor grade." (PMID 37081115, 2023). "In HCC, TRAF2 also promotes tumor growth by preventing ROS production, mitochondrial dysfunction and autophagy and contributes to drug resistance by supporting ER stress response." (PMID 40229245, 2025). "Our data from TRAF2 KO combined with Birinipant treatment indicated a significant depletion of RNF31 in the TNFR1 complex in sensitized tumor cells, despite unchanged cellular RNF31 protein levels." (PMID 41315176, 2025). "In contrast, loss of TRAF2 or autophagy induction promoted CD47 autophagic degradation and enhanced CD47 antibody anti‐tumor immunotherapy." (PMID 39665172, 2025). "We further explored the correlation between TRAF2 and dynamic immune-related features, including mismatch repair (MMR), tumor mutation burden (TMB), and microsatellite instability (MSI)." (PMID 40144665, 2025). "We observed that TRAF2 showed higher expression levels in T cells and tumor cells, which is consistent with the results in the enrichment analysis." (PMID 40144665, 2025). "According to our results, the three tumor types with the strongest correlation between TRAF2 expression and ImmuneScore were MESO, CESC, and BLCA." (PMID 40144665, 2025). "Western blot analysis using tumor lysates showed that TRAF2 knockout significantly reduced CD47 levels in response to rapamycin." (PMID 39665172, 2025). "TRAF2 seems to be required for tumor growth promotion by inhibiting apoptosis, promoting a malignant phenotype through EMT, regulating the sensitivity of certain cancer cells to chemotherapy and radiotherapy, and inducing immune suppression." (PMID 40229245, 2025). "We used The Human Protein Atlas (HPA) database, TIMER 2.0 database, and TCGA database to evaluate TRAF2 expression in human normal and tumor tissues." (PMID 40144665, 2025). "Although TRAF2 can act as a tumor suppressor, it is predominantly described as a tumor promoter, as its expression has been correlated with increased metastatic potential and poorer prognosis in several types of cancer." (PMID 40229245, 2025). "Dual targeting of TRAF2 and cIAP1/2 has been shown to sensitize a wide range of tumor cell lines across multiple cancer types to T cell killing." (PMID 41315176, 2025). "Consistent with previous findings, the knockdown of TRAF2 in PCa cells demonstrated effects on biological functions that align with its established role in promoting tumor growth and malignant activity." (PMID 40560737, 2025). "Further, we explored the details of malignancies and immune cell expression in LIHC through multiple single-cell datasets, examining TRAF2 expression in the tumor immune microenvironment (TIME)." (PMID 40144665, 2025). "In vivo, administration of 40 mg/kg Butein resulted in a 79% reduction in tumor volume and completely blocked the nuclear translocation of TRAF2." (PMID 41458609, 2025). "The results showed that rapamycin treatment significantly inhibited tumor growth in TRAF2 gene knockout implanted tumor model." (PMID 39665172, 2025). "We discovered a striking similarity between the TNF and T cell treatments, with nearly 90% of significantly upregulated phosphorylation sites shared between the two conditions in sensitized TRAF2 KO tumor cells." (PMID 41315176, 2025).
tumor (continued). "Although evidence indicates that TRAF2, by promoting the activation of NF-κB, enhances the CD8+-related anti-tumor immune response, hints to double-edged sword effects of TRAF2 hyperactivation are rare, indicating it as mostly pro-cancerogenic." (PMID 40229245, 2025). "Immunostaining analysis showed that TRAF2 knockout markedly increased the colocalization of tumor cells with macrophages, suggesting that TRAF2 knockout increased the macrophage phagocytosis." (PMID 39665172, 2025). "Immunohistochemical staining analysis using tumor tissues showed that TRAF2 protein level was higher in LUSC than that of normal tissue, which was consistent with high TRAF2 gene expression in LUSC." (PMID 39665172, 2025). "Studying TRAF2 is crucial for understanding tumor signaling and interactions within the TME, including its role in immune dynamics, chemoresistance, and metastasis." (PMID 40229245, 2025). "We elucidate how TRAF2’s signaling contributes to physiological functions as well as to cancer progression through direct mechanisms, inflammation, and the tumor microenvironment (TME), providing examples across cancer types." (PMID 40229245, 2025). "We found that TRAF2 is highly expressed in tumor cells and T cells (CD8Tex, Tprolif, Treg, CD8T, and CD4T cells)." (PMID 40144665, 2025). "In contrast, loss of TRAF2 facilitated CD47 autophagic degradation and inhibited tumor immune escape." (PMID 39665172, 2025). "Similar to KHDC4, the distribution of TRAF2 indicated a malignant cell type (highlighted in red) with the highest intensity level compared to other major cell lineages in the PCa tumor microenvironment (GSE176031)." (PMID 40560737, 2025). "In cancers, TRAF2 overexpression inhibits the apoptotic process while promoting angiogenesis, tumorigenesis and tumor progression." (PMID 40229245, 2025). "We next detected the effect of autophagy induction on tumor immune escape in TRAF2 gene knockout LLC cell implanted tumor model." (PMID 39665172, 2025). "It has been demonstrated that ERS can induce tumor cell apoptosis through the IRE1/TRAF2/ASK1/JNK pathway, the caspase-12 kinase pathway, and the C/EBP homologous protein (CHOP)/GADD153 pathway." (PMID 39080273, 2024). "Its knockdown enhances apoptosis, while downregulating SIRT1 expression in TRAIL-treated cells, indicating a TRAF2/SIRT1 axis that supports tumor survival and growth." (PMID 39796040, 2024). "In the context of HNSC, our findings indicate that TRAF1 and TRAF5 act as tumor suppressors, whereas TRAF2 emerges as an oncogenic factor." (PMID 38825674, 2024). "Another layer of complexity involves TNF receptor-associated factor 2 (TRAF2), a regulator of tumor progression and resistance to apoptosis in androgen-refractory PCa." (PMID 39796040, 2024). "Next, we conducted migration assays and invasion assays to investigate the effects of TRAF2 depletion on tumor cell migration and invasion potential." (PMID 37415241, 2023). "Consistent with negative regulation, TRAF2, TRAF3 and cIAPs inactivation mutation has been detected in B‐cell malignancy and their tumour suppressive function is mainly associated with non‐canonical NF‐κB inhibition." (PMID 36881608, 2023). "Recent studies have demonstrated that TRAF2 regulates tumor progression by through multiple pathways." (PMID 37415241, 2023). "As TRAF2 is required to interact with cIAP1 or cIAP2 to promote TNFR1‐induced NF‐κB signalling and suppress TNF‐induced cell death, inhibition of TRAF2 or cIAPs is necessary to sensitise tumour cells to TNF‐induced cell death." (PMID 36881608, 2023). "To further verify the role of TRAF2 in tumor growth in vivo, we established a xenograft model by injecting the paired sgCtrl and sgTRAF2 huh7 cells into nude mice." (PMID 37081115, 2023). "Motivated by our in intro phenotype of TRAF2 depletion, we next aimed to determine the effect of TRAF2 on ccRCC tumor growth and metastasis in vivo." (PMID 37415241, 2023).
tumor (continued). "TNFR1, caspase-8, FADD, RIPK1, the LUBAC components, TRAF2 and cIAP1 have all been identified in genome-wide Crispr/Cas9 screens as important factors involved in the control of tumor development by CD8+ T cells and NK cells." (PMID 38020877, 2023). "When mice were necropsied, mice in the TRAF2-depleted group showed reduced tumor burden compared with control mice." (PMID 37415241, 2023). "Birinapant was found to target TRAF2-related cIAP, activate caspase-8 and induce tumor cell death by eliminating TNF-induced NF-κB activation." (PMID 37415241, 2023). "The findings of our study reveal that TRAF2 promotes tumor growth and progression through autophagy activation-mediated macrophage M2 polarization, which undoubtedly expands our understanding of TRAF2 regulatory pathways." (PMID 37415241, 2023). "Intriguingly, TRAF2 and cIAP1 were furthermore found to be major sgRNA targets enhancing tumor cell killing under ICB." (PMID 38020877, 2023). "The immune microenvironment maintained by macrophages plays an important role in tumor angiogenesis, so we performed Western Blot experiments to detect the effect of TRAF2 depletion on tumor angiogenesis." (PMID 37415241, 2023). "illustrated that deletion of TNF receptor-associated factor 2 (TRAF2) redirected TNF signaling pathway to promote RIPK1-dependent apoptosis, thereby lowering TNF cytotoxicity threshold in tumor cells." (PMID 37876793, 2023). "Its expression is positively correlated with advanced tumor stages, poor prognosis and TRAF2 expression." (PMID 37077419, 2023). "Specifically, p62 knockdown partially abrogated growth suppression by TRAF2 depletion in both in vitro cell culture and in vivo xenograft models, thus acting as tumor-suppressing protein." (PMID 37081115, 2023). "Accordingly, it was furthermore reported that TRAF2-deficiency and treatment with TWEAK or IAP antagonists sensitize for tumor cell killing by CD8+ T cell/NK cell-derived TNF." (PMID 38020877, 2023). "In this respect, two independent groundbreaking studies give strong evidence that tumor cell-expressed TRAF2 antagonizes the efficacy of checkpoint inhibitor therapies by protection against cell death induction by CD8+-derived TNF." (PMID 37545514, 2023). "Orthotopic tumor growth assay results revealed that TRAF2 plays a key role as a promotor of ccRCC growth and metastasis." (PMID 37415241, 2023). "We found that TRAF2 depletion decreased tumor growth, tumor weight, and tumor cell Ki67 positive rate in mice models of orthotopic transplantation." (PMID 37415241, 2023). "Taken together, p62 knockdown partially rescued tumor growth suppression both in vitro and in vivo by TRAF2 knockdown, via at least in part, reactivation of mTORC1 activity." (PMID 37081115, 2023). "More importantly, our study reveals that TRAF2 promotes the interaction between macrophages and tumor cells in an autophagy-dependent pathway, thereby promoting the malignant progression of ccRCC." (PMID 37415241, 2023). "For example, we found that ERBB2 is enriched in the tumor region detected by SpatialPCA while TRAF2 is enriched in the tumor surrounding region detected by SpatialPCA." (PMID 36418351, 2022). "CHMP2B, CHMP6, and RIPK3 were downregulated, while CXCL1, GPX4, and TRAF2 were upregulated in tumor samples." (PMID 36046241, 2022). "We have shown that proteasomal inhibition activated IRE1α to recruit TRAF2 and activate NF‐κB to transcribe inflammatory cytokine and chemokine, thus creating a favorable tumor microenvironment for immunotherapy." (PMID 34898004, 2022). "A second conclusion is that TRAF2, despite its function as a tumor suppressor in B-cells, is a promising target for tumor therapy, particularly in combination with checkpoint inhibitors." (PMID 36011046, 2022). "In complete agreement with our epigenetic profiling data, gene expression of FAS, FASLG, TNFSF10, TRAF1 and TRAF2 was higher in the clusters corresponding to dysfunctional tumor-infiltrating CD8+ T cells." (PMID 35668194, 2022).